USP37 (ubiquitin specific peptidase 37)
Diseases named in the same sentence as USP37 in open-access papers (continued):
Sharing a sentence is not in itself a finding about the gene and the disease.
cancer (continued). "Our results indicated that from both OS and DSS analyses were consistent, indicating that USP37 is a significant prognostic factor across a wide range of cancers." (PMID 40926837, 2025). "In summary, USP37 shows varying expression across tissues and cancers, with higher levels in several tumors, especially PAAD, and is mainly localized in the nucleus of tumor cells." (PMID 40926837, 2025). "To identify USP37-associated cancer hallmarks, we performed gene set enrichment analysis (GSEA) using differentially expressed genes (DEGs) between low and high USP37 expression subgroups for each cancer type." (PMID 40926837, 2025). "We utilized the Kaplan-Meier method along with univariate Cox regression analysis to assess the prognostic significance of USP37 in a pan-cancer context." (PMID 40926837, 2025). "Consistently, the expression of mesenchymal biomarkers N-Cadherin, Vimentin and Snail and cancer stemness biomarkers USP37, ALDH1, OCT4 and Smo/Gli-1 in BC cells was suppressed by CYT and markedly recovered by SRSF1 overexpression." (PMID 40176901, 2025). "To further explore USP37 expression in cancers, we analyzed mRNA levels from TCGA and GTEx datasets across multiple tumor types." (PMID 40926837, 2025). "It is known that USP37 is a member of the deubiquitinase family and can prevent the degradation of cancer proteins by deubiquitinating them in cancer." (PMID 38516408, 2024). "USP37 plays an important role in promoting cancer cell migration, downregulating E-cadherin, and upregulating wave protein by stabilizing Snail expression." (PMID 38516408, 2024). "USP37 is a Deubiquitinating enzyme that cleaves attached ubiquitin, destabilizing oncoproteins and regulating critical cellular processes in various cancer types." (PMID 37118828, 2023). "The reported deubiquitinases of MYC include USP22, USP28, USP29, USP36 and USP37, and they enhance cancer stemness via BMI1, LSD1 Snail and CEP63 stabilization, respectively." (PMID 36765885, 2023). "In this study, the Cancer Genome Atlas (TCGA) database was analyzed to investigate USP37 expression." (PMID 37118828, 2023). "We also discuss the influence of USP37 on a myriad of signaling pathways and the potential of these pathways for novel therapeutic interventions in cancers." (PMID 34758854, 2021). "Our TCGA data analysis correlates with observation of various studies that elevated expression of USP37 in different cancers is requisite for cell proliferation and tumorigenesis." (PMID 34758854, 2021). "Additional studies accentuate that various oncoproteins were stabilised by USP37 and high expression of USP37 results in poor prognosis of other cancers." (PMID 34758854, 2021). "Recent studies have conclusively established that USP37 stabilizes many oncoproteins involved in regulating various hallmarks of cancer." (PMID 34758854, 2021). "We next examined the role of the USP37–BLM axis in the response to chemo or radiotherapy in human cancer cells." (PMID 34606619, 2021). "This review emphasizes the importance of USP37 in cancer and how identifying its molecular targets and signalling networks in various cancer types can help advance cancer therapeutics." (PMID 34758854, 2021). "The biological role of USP37 and evidence of its oncogenic potential in different cancers is conclusively established." (PMID 34758854, 2021). "Further interacting partners as in regulating USP37 and downstream targets need to be elucidated to understand the mechanistic role of elevated USP37 in various cancers." (PMID 34758854, 2021). "USP37 immunoreactivity was significantly higher in the cytoplasm of MCF-7/ADR cells than in the non-cancer MCF-10A cells." (PMID 33390801, 2021). "Several aspects of USP37 biology in cancer cells are yet unclear and are an active area of research." (PMID 34758854, 2021).
cancer (continued). "USP37 was also reported to remove ubiquitin chains from Cyclin A and overexpression of USP37 promotes Cyclin A accumulation and accelerated S phase entry, suggesting a potentially key role for USP37 in regulating the cell cycle in a cancer setting." (PMID 34606619, 2021). "Recently, a series of studies have demonstrated that USP37 is involved in carcinoma occurrence and progression." (PMID 33390801, 2021). "Analysis of the TCGA database indicated that cancer with USP37 transcripts (n = 517) had a significantly higher expression level than normal samples (n = 29) (P < 0.0001)." (PMID 30482232, 2018). "The results indicated that cancer with higher expression levels of USP37 was significantly correlated with the elevated rates of mortality (P < 0.05)." (PMID 30482232, 2018). "Our results demonstrate that knock-down of USP37 plays a critical role in the progression of cancer by decreasing the ubiquitination and stability of 14-3-3γ." (PMID 26427597, 2015). "Taken together, the results suggest that USP37 can be considered a therapeutic target for the regulation of cell proliferation and a biomarker of tumorigenesis in cancers." (PMID 26427597, 2015). "Based on our experimental results, USP37 appears to play an important role in cell proliferation in cancer, regulating the stability of 14-3-3γ." (PMID 26427597, 2015). "The findings on the regulation of 14-3-3γ ubiquitination by USP37 establish a new role for USP37 in cancer cell proliferation, indicating that ubiquitination, a PTM, has an important role in cancer." (PMID 26427597, 2015). "Genomic alterations in USP37 across multiple cancer types were examined using cBioPortal." (PMID 40926837, 2025). "Overall, these results suggest that USP37 may serve as a prognostic predictor across various cancers." (PMID 40926837, 2025). "Taken together, these findings suggest that USP37 could be a valuable prognostic biomarker in cancer, offering insight into patient outcomes and aiding in the development of personalized therapeutic strategies." (PMID 40926837, 2025). "In the pathway enrichment analysis, USP37 expression was found to be positively correlated with key cell cycle-related pathways, including the mitotic spindle, G2M checkpoint, and E2F targets in most majority of cancers." (PMID 40926837, 2025). "Since stabilization of c-MYC by different USPs in different cancers is underpinned by direct physical interaction between both molecules including USP37, it is, therefore, also conceivable that in the ABC subtype of DLBCL, c-MYC is likely regulated by direct interaction with USP37." (PMID 36985413, 2023). "It will be interesting to determine whether the increased expression of USP37 in cancer reflects both an ability to drive replication as well as enhancing the ability to deal with replication stress caused by rapid cell cycle progression." (PMID 34509474, 2021). "To further investigate the potential role of the USP37–BLM axis as a target for cancer therapy, we knocked down USP37 or BLM individually or together in MCF7 cells or MDA-MB-231 cells with high USP37 level, and examined the cell survival following cisplatin or IR treatment." (PMID 34606619, 2021). "Targeting USP37 alone or in combination with other drugs may be an excellent approach to achieve synthetic lethality in cancer cells." (PMID 34758854, 2021). "Because DDR pathways are critical for drug resistance in cancers, a clear understanding of the role of USP37 in regulating these pathways may address drug resistance in some cancers." (PMID 34758854, 2021). "This suggests that many facets of USP37 biology should be investigated by determining its different substrates in the context of different cancers because the distinct tumor microenvironment may influence its activity and substrate selection." (PMID 34758854, 2021). "We performed TCGA data analysis to examine the USP37 expression profile in different cancers." (PMID 34758854, 2021).
cancer (continued). "Therefore, the functioning of USP37 in different cancers is dependent upon the cancer microenvironment." (PMID 34758854, 2021). "Next, we analyzed the cell proliferation in these cells with or without cisplatin treatment and found reconstituted with USP37 WT but not S114A (phosphorylation-deficient) mutant led cancer cell resistant to cisplatin treatment in vitro." (PMID 34606619, 2021). "In summary, these data suggest that USP37 plays important roles in tumorigenesis and metastasis and may be a new therapeutic target to treat cancer and prognosis marker for NSCLC patients." (PMID 31998374, 2019). "The demonstration that knockdown of USP37 decreases the stability of these oncogenic proteins, raises the possibility that specific and potent inhibitors of USP37 may provide a viable therapeutic strategy to treat human cancers." (PMID 30858488, 2019). "We found that the expression level of USP37 was higher in cancer cells." (PMID 26427597, 2015). "Recent reports demonstrated that USP37 had diverse regulatory functions in the cellular signaling pathway and that these played a role in malignancy, including promoting the proliferation and viability of cancer cells." (PMID 26427597, 2015). "Thus, we estimated the expression level of USP37 in various cancer cells and in normal cells, such as human skin fibroblasts." (PMID 26427597, 2015). "In addition, we compared the endogenous expression levels of USP37 and 14-3-3γ in various cancer cell lines with those in normal cells and found lower expression levels of these proteins in the normal cells." (PMID 26427597, 2015). "Apart from its physiological relevance, USP37 is also reported to play an important role in cancer." (PMID 25347529, 2014). "Interestingly, not many replicative genes associated with USP37 were found in the analysis, but these genes need to be validated as they may provide insight into the physiological role of USP37 beyond cancer." (PMID 37118828, 2023). "Furthermore, USP37 was also elevated at the protein level in cancer stem cell spheroids compared to adherent cells, and its knockdown (KD) decreased expression of stem cell markers like smoothened, Gli-1, ALDH1, and OCT4 and inhibited stable spheroid formation." (PMID 34758854, 2021). "The role of USP37 in cancer progression depends on many unknown factors, and cancer-specific studies of USP37 functioning are required to understand the whole interactome and expression profiling to further mark it as an oncogene or a tumor suppressor factor in different cancers." (PMID 34758854, 2021). "Therefore, we investigated whether 14-3-3γ mediates proliferation in cancer cells, and 14-3-3γ by USP37 is responsible for promoting cell proliferation." (PMID 26427597, 2015). "Thus, we examined whether knock-down of USP37 decreased cancer cell growth by downregulation of 14-3-3γ." (PMID 26427597, 2015). "Besides, its normal functions, USP37 is gaining relevance in context of cancer development." (PMID 25347529, 2014). "USP35, USP36, USP37, USP47, USP49, and OTUD6B play crucial roles in cancer progression and chemoresistance across various cancers, including NSCLC." (PMID 41399373, 2026). "Furthermore, since the catalytic activity of USP37 is essential to protect against topoisomerase inhibitors and replication-stalling agents, our work suggests that USP37 inhibitors might be selectively toxic to cancer cells exhibiting elevated replication stress." (PMID 40533495, 2025). "These DUBs (USP22, USP28, USP29, USP36, USP37 and OTUD6A) are observed in stabilizing MYC in cancer cells." (PMID 36765885, 2023). "Our data demonstrated that USP37 downregulation enhanced the inhibitory effect of adriamycin on MCF-7 and MCF-7/ADR cancer cells through the inhibition of Bcl-2/Bax signaling pathway." (PMID 33390801, 2021).
cancer (continued). "Although the meaning of this interaction in terms of CHK1 activity will require additional studies, our finding that USP37 is required for full CHK1 activity provide new insight into the functions of this DUB in both cell and cancer biology." (PMID 34509474, 2021). "USP37 regulates replication stress by stabilizing CDT1 and CHK1, but these findings must be validated for different cancers." (PMID 34758854, 2021). "Of these three DUBs, USP37 binds SNAI1 most strongly and plays a major role in stabilizing SNAI1 and thereby promoting cancer cell migration, E cadherin downregulation, and vimentin upregulation." (PMID 34758854, 2021). "For example, the methylation regions located in ACAA2, NUSAP1, OGFOD1, PSMD5, SNRNP40, USP37 and XRCC6 are shared by five cancers (i.e., BRCA, CESC, COAD, KIRP and SARC)." (PMID 34464378, 2021). "Collectively, our results establish a novel molecular mechanism for the USP37–BLM axis in regulating DSB repair with an important role in chemotherapy and radiotherapy response in human cancers." (PMID 34606619, 2021). "Therefore, the function of USP37 in different cancer types may be context-specific." (PMID 34758854, 2021). "Taken all together, USP37 has tumorigenic potential following MAPK pathway by stabilization of 14-3-3γ and plays an important role in cancer progression." (PMID 26427597, 2015). "USP36, USP37, USP47, and OTUD6B exert its oncogenic effects by stabilizing key oncoproteins, such as cellular myelocytomatosis oncogene (c-Myc), 14-3-3γ, Snail, and β-catenin, thereby promoting cancer cell proliferation, migration, and invasion 27-32." (PMID 41399373, 2026). "We firstly observed that USP37 is aberrantly expressed in PAAD tissues, suggesting that it could contribute to cancer progression." (PMID 40926837, 2025). "Additionally, USP37 demonstrated a significant positive relationship with ADORA2A, CD160, TNFSF15 and NRP1 across the majority of cancers." (PMID 40926837, 2025). "Despite preliminary investigations into the role of USP37 in some tumors, there is currently a lack of pan-cancer analyses focusing on the USP37 gene." (PMID 40926837, 2025). "Moreover, a catalytically dead USP37 mutant cannot promote cancer cell migration, indicating that the DUB activity of USP37 is required for its metastatic properties." (PMID 34758854, 2021). "As USP37 is a specific DUB for 14-3-3γ, it might provide an effective and selective target for novel cancer therapies." (PMID 26427597, 2015). "Indeed, a plethora of cancer cell lines appear to have either lost (USP26 = 1457/USP37 = 446; COSMIC) or amplified (USP26 = 309/USP37 = 359; COSMIC) the expression of these DUBs." (PMID 26101254, 2015). "Additionally, DNA methylation patterns suggest that the expression of USP37 may be regulated epigenetically, contributing to its aberrant expression in PAAD and potentially other cancers." (PMID 40926837, 2025). "Notably, our results showed that overexpression of USP37, but not USP37 (C350S), enhanced the proliferation of cancer cells when 14-3-3γ was co-transfected." (PMID 26427597, 2015). "When all these findings are considered together, USP37 is shown to be a specific DUB that prevents 14-3-3γ degradation, which may contribute to malignant transformation via MAPK signaling pathway, possibly providing a new target for therapeutic objectives of cancer." (PMID 26427597, 2015).
tumor (11 papers, 2018 to 2025). "Based on our observations, we propose that PCNA serves as a docking site for replication factors regulated by USP37, which helps the cells to manage replication stress associated with the tumor microenvironment." (PMID 37118828, 2023). "Analysis of USP37 genomic alterations revealed its mutations in several tumor types." (PMID 40926837, 2025). "Moreover, the relationships between USP37, TMB, and MSI suggest that USP37 may be linked with tumor heterogeneity and the mutational environment in PAAD." (PMID 40926837, 2025). "Positive correlations between tumor mutation burden TMB and USP37 expression were observed in UCEC, THYM, STAD, SKCM, LUAD, LAML, and COAD." (PMID 40926837, 2025). "In contrast, USP37-overexpressing PANC-1 cells showed markedly increased tumor growth and weight compared to controls." (PMID 40926837, 2025). "Immunofluorescence (IF) imaging revealed that the USP37 protein predominantly localized in the nuclei of U2-OS and U-251MG tumor cells, with minimal cytoplasmic expression." (PMID 40926837, 2025). "Next, we performed qRT-PCR and Western blot assays on clinical PAAD samples to validate the expression levels of USP37 in comparison to adjacent non-tumor tissues." (PMID 40926837, 2025). "We found that lower expression level of USP37 obviously impaired the expression of Hh targets (Smo and Gli-1) and cell proliferation marker Ki-67 in the tumor tissues as seen by immunohistochemical staining." (PMID 30482232, 2018). "Ubiquitin-specific peptidase 37 (USP37), a novel DUB, was identified to be a potential factor associated with tumor progression." (PMID 30482232, 2018). "This suggests that the functional consequences of USP37 dysregulation maybe be critically dependent on the cellular and microenvironmental context of the specific tumor type." (PMID 40926837, 2025). "Future studies on USP37’s influence on the tumor microenvironment could provide invaluable information for designing combination therapies that enhance immune responses in PAAD." (PMID 40926837, 2025). "highlighted the prominent role of USP37 in promoting tumor metastasis." (PMID 40458725, 2025). "In KIRC, characterized by frequent VHL inactivation and constitutive HIF signaling, USP37 may preferentially target and stabilize substrates that exert tumor-suppressive or immunomodulatory functions." (PMID 40926837, 2025). "CDH1 is a postulated tumor suppressor, and USP37 may thus act as a tumor suppressor in concert with CDH1." (PMID 34758854, 2021). "USP37 function may be modulated in the neural microenvironment by some unknown modifications that promote its tumor suppressor function." (PMID 34758854, 2021). "By in vivo assay, USP37 downregulation also suppressed the tumor growth of MCF-7/ADR cells." (PMID 33390801, 2021). "Moreover, our in vivo experiments, using subcutaneous xenograft models, reinforced these findings by showing that USP37 knockdown in SW1990 cells led to significantly reduced tumor growth, whereas USP37 overexpression in PANC-1 cells resulted in enhanced tumor size and weight." (PMID 40926837, 2025). "Moreover, studies have shown that USP37 is closely related to tumor metastasis." (PMID 40458725, 2025). "Research has shown that reducing CDT1 expression can significantly inhibit the malignant behavior of HCC cells, which indicates that USP37 may influence tumor progression by modulating the activity of CDT1 and other interacting proteins, requiring further investigation." (PMID 40926837, 2025). "Notably, oxidative phosphorylation, myogenesis, and allograft rejection pathways show a negative correlation with USP37 expression across most tumor types, while its expression is positively associated with the mitotic spindle, G2M checkpoint, and E2F target pathways." (PMID 40926837, 2025). "Through deubiquitination, USP37 increases Snail stability, promotes the EMT, and ultimately promotes the spread and metastasis of tumor cells." (PMID 40458725, 2025).